PML (PML nuclear body scaffold)
Diseases named in the same sentence as PML in open-access papers (continued):
Sharing a sentence is not in itself a finding about the gene and the disease.
infection (continued). "The accumulation of TCRV Z protein during infection enhances the induction of apoptosis, hence it could be speculated that TCRV utilises this pathway to facilitate replication through a mechanism that involves PML-TCRV Z interactions." (PMID 32708250, 2020). "However, during WT infection, ICP0 induced PML degradation and the dispersal of the PML-NB restriction factors, highlighting the importance of ICP0 in the release of viral genomes entrapped within PML-NBs to stimulate the onset of lytic HSV-1 replication." (PMID 31781083, 2019). "We would not expect to detect much PML at 7 hours after infection." (PMID 31725813, 2019). "Under replication-competent infection conditions, our transcriptomic and infection biology analysis clearly demonstrate that HIRA plays important roles in the induction of innate immune defences and ISG expression during HSV-1 infection that correlates with its enrichment of localization at PML-NBs." (PMID 30901352, 2019). "Finally, we demonstrate that the effect on IE in THP1 cells is specific for reactivation, as the WT and mutant viruses displayed no differential capacity to establish lytic infections of control and PML KO THP1 cells." (PMID 30021158, 2018). "Instead, IE72 promotes PML deSUMOylation but not degradation in lytic infection." (PMID 30021158, 2018). "Whether PML has an impact or not on the infection of human cells by HIV-1 has been an open question for over 15 years." (PMID 28656178, 2017). "However, it was clear that IFN-β efficiently inhibited infection in the presence or absence of PML, indicating that PML is not crucial for the IFN-I-mediated antiretroviral response." (PMID 28656178, 2017). "Thus, PML is important for IFN-I to inhibit the early infection stages of SIVmac, but not of HIV-1, in Jurkat cells." (PMID 28656178, 2017). "Thus, although possible, unless more direct evidence is provided, one should not consider that both HSV-1 and HCMV genomes interact with PML-NBs in the same way during immediate early phases of infection." (PMID 27782081, 2016). "The PML-mediated block to infection is independent of the HIV promoter activity." (PMID 26703718, 2015). "To determine whether this relocalization could also explain the effect of PML on HIV reverse transcription in primary HFF cells, we analyzed the cellular localization of PML at various time points upon infection with VSV-G pseudotyped, fluorescently labeled HIV particles (HIV-MAGFP)." (PMID 26703718, 2015). "Similarly, the infection with increasing amounts of the HIV-luciferase virus was enhanced only in the absence of PML but not in the absence of Sp100 or Daxx." (PMID 26703718, 2015). "The IE1(Δ290–320) protein failed to disrupt PML NBs during infection." (PMID 25812002, 2015). "In summary, by investigating the in vitro latency model of THP-1 cells, this study provides evidence that PML, hDaxx and Sp100 do not act as critical determinants for the establishment of a quiescent state after infection of monocytes with human cytomegalovirus." (PMID 26057166, 2015). "In contrast to the large DNA viruses, infection with polyomaviruses does not grossly disrupt the morphology of PML-NBs, although their number and size may increase and alterations in their function may be detected." (PMID 22496654, 2012). "However EBNA1 did not positively contribute to lytic infection when the PML proteins were silenced, suggesting that the role of EBNA1 in lytic infection was in overcoming suppression by PML proteins." (PMID 24278697, 2012). "PML-NB reorganization and co-localization with HSV-1 genomes were observed as early events in lytic infection in cultured cells, raising the possibility that the association we observed during latency could be initiated early during the establishment of latency (the acute phase)." (PMID 22912575, 2012).
infection (continued). "These interactions were proposed to support infection by directing the viral genome to replication compartments or facilitating virion assembly but enhancing or inhibitory effects of specific PML isoforms on viral replication could not be assessed." (PMID 21304940, 2011). "For proteins that are only present later in infection, the disruption of PML NBs may not be the contribution of the protein to infection, as PML NBs would already be disrupted through the action of other proteins." (PMID 18617993, 2008). "Thus, after 24 hours of IFN treatment cPMLΔ5&6 levels were not enhanced compared to total PML, but at 24 hours post infection, cPMLΔ5&6 transcripts represented about 25% of all PML transcripts." (PMID 18509536, 2008). "In contrast, we observed that during infection with particles from pHBV1.1 Δscm1/2-transfected cells, the cytoplasmic HBV core fraction was enhanced to 80%, while only 20% was found at the border of the nuclear DAPI staining; nothing could be detected in either the nuclear or the PML-NB fraction." (PMID 37199632, 2023). "Thus, ICP0 can induce the destabilization of PML-NBs and centromeric chromatin, contributing to the establishment of a suitable nuclear environment for lytic infection, and ICP4 plays a major regulatory role in gene transcription and is necessary for HSV to undergo lytic infection." (PMID 33013729, 2020). "Interestingly, we could observe this effect for PML only during lytic reactivation and not during a de novo infection which is in accordance with previously reported findings." (PMID 31059555, 2019). "Nor can we discount a repressive role for HIRA at PML-NBs in other infection contexts, for example during the establishment of viral latency in sensory neurones, where the presence or absence of specific viral or cellular factors may influence the mechanism of viral chromatin assembly and silencing." (PMID 30901352, 2019). "Hence, PML NBs reorganize in structures called viral DNA-containing PML NBs (vDCP NBs), which are formed at early times during the process of HSV-1 latency establishment and persist during latency per se in a large subset of latently infected neurons in a mouse model of infection." (PMID 30235352, 2018). "SARS-CoV-2 infection did not upregulate PML protein levels, while treatment of the cells with human IFN-β and or infection with RSV resulted in a robust induction of PML." (PMID 37022178, 2023). "We then examined ATRX, an ND10 constituent that is not degraded but is dispersed upon PML degradation, to observe ATRX localization relative to eCFP-PML I in late infection." (PMID 37243155, 2023). "After infection with HCMV-IE2eYFP, PML aggregates were completely dispersed and, in accordance, no fiber-like structures were detected in EM images." (PMID 35319461, 2022). "Unlike other viruses that dissociate PML NBs, HPV takes advantage of their disassembly during mitosis and utilizes them as a new protection device to finally establish infection." (PMID 32154186, 2020). "In the absence of ICP0, PML and other PML NB proteins act to suppress HSV-1 gene expression and restrict infection, highlighting the intrinsic antiviral function of PML NBs and the requirement of HSV-1 to antagonize this aspect of PML NB function." (PMID 32013091, 2020). "We show that PML is dispensable for the restriction of lentiviruses in human cells, is not involved in the IFN-I-mediated inhibition of infection, and is not relevant to the inhibition of TRIM5α by As2O3." (PMID 28656178, 2017). "These events trigger an antibacterial response that is not observed during in vitro infection by an LLO-defective Listeria mutant, but which can be phenocopied by specific induction of PML de-SUMOylation." (PMID 28074026, 2017). "These infections were performed in the presence or absence of IFN-β, owing to the reported role of PML in stimulating the transcription of ISGs." (PMID 28656178, 2017).
infection (continued). "We also confirmed our mass spectrometry data that RanGAP1 and PML are basally SUMOylated but largely do not change in modification status following IAV infection, whereas TRIM28 is highly deSUMOylated during infection." (PMID 26549460, 2015). "After infection of non-differentiated THP-1 cells, we observed that an shRNA-mediated depletion of PML, hDaxx or Sp100 did not affect the initiation of viral IE gene expression." (PMID 26057166, 2015). "One of the proteins absent from infected cells, PML, is subject to ubiquitin-mediated degradation during MHV68 infection." (PMID 24068923, 2013). "A disruption of PML-NBs was also observed during the course of DENV infection, although it was not investigated whether this was due to the infection itself." (PMID 39205236, 2024). "Indeed, while HPV depends on PML for its efficient transcription and may therefore not fully profit from the enhanced nuclear access, other viruses that do not need or even target and dissociate PML NBs for establishing productive infection may thrive even more in such a setting." (PMID 38485766, 2024). "Perhaps counterintuitively this absence of PML bodies during latency is not, in itself, sufficient for reactivation of the HCMV MIEP; infection of undifferentiated myeloid cell lines in which PML has been knocked‐out still results in MIEP repression and the establishment of latency." (PMID 38009611, 2023). "Moreover, it was observed that SP100 degradation was delayed in PML-/-infected cells and that the accumulation of ICP0 was reduced at low but not high multiplication of infection." (PMID 32545507, 2020). "Thus, PML restricts the early stages of HIV-1 and SIVmac infection but does not affect viral gene expression in SupT1 cells." (PMID 27000403, 2016). "Furthermore, we did not see a rearrangement of PML-NBs such as observed during BKV infection, although a slight increase in the size of PML-NBs during infection was noted." (PMID 22496654, 2012). "In infected HELF, PML-NBs did not colocalize with viral DNA replication compartments, which were identified by ORF29 and IE62 expression, at this late time at 24 hr after infection." (PMID 21304940, 2011). "Interestingly, even in PML-depleted cells, ICP0 colocalized with SUMO-2/3 conjugates, but not SUMO-1 conjugates, at the earliest stages of infection when only very low levels of ICP0 were present." (PMID 21949651, 2011). "Indeed a previous study examined PML NBs in B-cells latently infected with EBV (both latency and I and latency III forms of infection) and found no obvious difference from uninfected cells." (PMID 18833293, 2008). "Therefore, PML, hDaxx, and Sp100 could indeed induce silencing of the HHV-6A genome, resulting in a quiescent infection rather than lytic replication." (PMID 30060604, 2018). "Thus, although individual PML isoforms modestly modulated the permissiveness to infection by the SIVmac, EIAV, and B-MLV vectors in a virus-specific fashion, none of them affected permissiveness to infection by the HIV-1 vector." (PMID 28656178, 2017).
neurodegenerative disease (8 papers, 2011 to 2026). A disorder of the central nervous system characterized by gradual and progressive loss of neural tissue and neurologic function. "The association between PML nuclear bodies and clastosomes has been implicated in the clearance of toxic mutant proteins associated with certain neurodegenerative diseases." (PMID 42311938, 2026). "In some cases, PML is upregulated or PML nuclear bodies are rearranged or disrupted in response to these proteins and in the neurodegenerative diseases caused by these proteins." (PMID 24062991, 2013). "Based on these findings, we propose that PML (also known as TRIM19) or other TRIMs can be functionalized for the activation of disaggregase pathways to limit the formation of pathological inclusions in neurodegenerative disease." (PMID 40246979, 2025). "Whether targeting PML is a good therapeutic strategy for the treatment of neurodegenerative diseases awaits for further evaluation." (PMID 29416846, 2018). "PML was reported to clear the CNS of toxic protein aggregates in neurodegenerative disease models." (PMID 29416846, 2018). "The PML-NBs closely resemble those that retain polyQ proteins in neurodegenerative diseases." (PMID 21304940, 2011).
hematological malignancies (6 papers, 2019 to 2023). "Here, we will briefly summarize these aspects to focus on the emerging role of PML as an under-recognized hub enforcing response of hematological malignancies to different therapies." (PMID 37382966, 2023). "PML is required for response or even cure of some hematological malignancies." (PMID 37382966, 2023).
bacterial infection (4 papers, 2015 to 2023). "The detrimental granulomatous lesion, botryomycosis, has been observed when bacterial infection occurred in Pml−/− mice due to impaired macrophage function, suggesting that PML is a regulator of inmate immunity." (PMID 29416846, 2018). "The studies herein have identified the downstream ISGs TNRFSF10A, PML, MYD88, EHD4, and HK2 that potentiate secondary bacterial infection." (PMID 37939149, 2023). "In addition, a further 12 ISGs of 380 tested ISGs including STAT1, STAT2, JAK1, IRF9, IRF2, IRF7 are key elements of IFN signaling, and classical and well-known ISGs such as ISG15, PKR, MX1, IFIT1, PML, IFI27 play key roles in viral or bacterial infections." (PMID 30717477, 2019). "To date, the role of PML-NBs in bacterial infection has not been explored, however PML is required for sensitivity to lippopolysaccharide (LPS)-induced septic shock indicating a role for PML in innate immunity to bacterial pathogens." (PMID 25848798, 2015).
cardiovascular diseases (3 papers, 2012 to 2023). "There is, however, little knowledge about the transcriptional regulation of PML, especially in cardiovascular diseases." (PMID 36778116, 2023). "However, the function of PML in cardiovascular disorders has only recently begun to be elucidated." (PMID 28525371, 2017).
colorectal (2 papers, 2020 to 2021). "The up-regulation of PCID2 suppressed PML by promoting its UPS-mediated degradation, which in turn, releases β-catenin to engage canonical Wnt/β-catenin signaling, thus contributing to colorectal tumorigenesis." (PMID 34625711, 2021).
genetic disorder (1 paper, 2024). "In the genetic disorder APL, PML is fused to the retinoic acid receptor alpha, resulting in the aberrant track-like structure of promyelocytic leukemia nuclear bodies, leading to the complete loss of PML-NB functionality (57, –, 59)." (PMID 38567974, 2024).
neurological disorders (1 paper, 2019). "Such protein inclusions, which are involved in the pathogenesis of several neurological disorders, are known to co-localize with PML bodies, and PML has been shown to promote their degradation." (PMID 31416160, 2019).
overlap syndrome (1 paper, 2022). "The distribution of each autoantibody by IB among two patients with overlap syndrome was PML which was positive only in the first patient, and Sp100 was positive in the second patient." (PMID 36422475, 2022).
retinopathies (1 paper, 2023).
PML also shares sentences with these, for which no sentence is quoted: acute lymphoblastic leukemia (5 papers); myeloproliferative neoplasm (4); chronic lymphocytic leukemia (3); CNS tumors (3); germ cell tumor (3); Hodgkins lymphoma (3); adult T-cell leukemia/lymphoma (2); Arrhythmia (2); atherosclerosis (2); blood cancer (2); cardiac hypertrophy (2); hematologic cancers (2); laryngeal carcinoma (2); metastatic prostate carcinoma (2); primary Sjogren’s syndrome (2); spinocerebellar ataxia 1 (2); squamous cell carcinoma (2); acute monoblastic leukemia (1); adenoma (1); Alpha-thalassemia (1); astrocytomas (1); autoimmune disease (1); B-cell acute lymphocytic leukaemia (1); cervical squamous cell carcinoma (1); childhood leukemia (1); cholangiocarcinoma (1); chondroblastoma (1); chondrosarcoma (1); chronic myelomonocytic leukemia (1); coagulopathy (1).
A further 41 diseases each share a sentence with PML in 1 paper.